FGF23 (fibroblast growth factor 23)
Diseases named in the same sentence as FGF23 in open-access papers (continued):
Sharing a sentence is not in itself a finding about the gene and the disease.
osteomalacia (continued). "This review highlights emerging pharmacologic treatments, including denosumab, a monoclonal antibody that has shown promise in reducing lesion size and pain in FD patients, and burosumab, a monoclonal antibody targeting FGF23, which reduces renal phosphate wasting and osteomalacia in FD patients." (PMID 40538772, 2025). "Y sobretodo, es una valiosa herramienta diagnóstica en las alteraciones primarias que cursan con exceso de FGF23, como los raquitismos hipofosfatémicos o los tumores inductores de osteomalacia donde, además es diana terapeútica tras el desarrollo de un anticuerpo anti-FGF23 (Burosumab)." (PMID 38634083, 2024). "The anti-FGF23 monoclonal antibody drug (KRN23) that has been developed to treat tumour-induced osteomalacia may have the potential to be re-purposed as an anti-UPSb therapeutic." (PMID 38397231, 2024). "However, adherence is a concern for patients with FGF23‐related hypophosphatemic rickets/osteomalacia who require long‐term treatment, as the drug requires subcutaneous injection once a month in adults and twice a month in children." (PMID 38050660, 2024). "However, serial analysis of gene expression identified DMP1 and PHEX as overexpressed genes in tumors responsible for tumor-induced osteomalacia and secreting FGF23." (PMID 36776964, 2023). "Dietary Pi supplementation aggravates FGF23 excess, rickets, and osteomalacia in adult Dmp1KO mice." (PMID 37943605, 2023). "In Japan, it is approved for all patients with FGF23-related hypophosphatemic rickets/osteomalacia." (PMID 36246908, 2022). "FGF23 excess can be congenital, as determined by inherited, genetically determined disorders of phosphate metabolism, and can manifest in infancy with FGF23-dependent hypophosphatemic rickets, or acquired in adults in tumor-induced osteomalacia." (PMID 36499221, 2022). "Both patients had no genetic mutation related to hereditary FGF23-related hypophosphatemic rickets/osteomalacia, including autosomal dominant hypophosphatemic rickets/osteomalacia (ADHR)." (PMID 34901334, 2021). "DMP1 is a suppressor of FGF23 as inactivating mutations in DMP1 result in autosomal recessive hypophosphatemic rickets (ARHR), a disease where overproduction of FGF23 results in renal phosphate wasting, osteomalacia, and rickets." (PMID 33716961, 2021). "However, the whole genome sequencing data contrasted our expectations: no mutations in FGF23 responsible for ADHR, and in the other genes related to the development of other hereditary FGF23-related hypophosphatemic rickets/osteomalacia." (PMID 34901334, 2021). "•Alcohol-induced FGF23-related osteomalacia is a totally new and distinct phenomenon." (PMID 34901334, 2021). "Through optimization of the delivery platform, we demonstrated that treatment with AAV-cFGF23 inhibited FGF23 signaling in kidney, resulting in increased expression of the Npt2a transporter and complete rescue of bone mineralization and osteomalacia in a mouse model of XLH." (PMID 34705504, 2021). "This suggests the possibility that iron supplementation could help prevent rickets and osteomalacia in individuals with an impaired ability to regulate FGF23 concentration." (PMID 33675347, 2021). "Patients with tumor-induced osteomalacia have very high plasma levels of FGF23." (PMID 33660084, 2021). "Recently, the involvement of FGF23, an osteocyte-borne hormone, in osteomalacia has been suggested." (PMID 33567797, 2021). "Therefore, whole genome sequencing was performed to examine the genes related to hereditary FGF23-related hypophosphatemic rickets/osteomalacia and those related to the development of autoimmune diseases." (PMID 34901334, 2021). "Interestingly, recent in vitro studies have demonstrated that HIF-1 mediates FGF23 production in tumor-induced osteomalacia (TIO), a rare paraneoplastic syndrome characterized by the aberrant production of FGF23." (PMID 31542779, 2019).
osteomalacia (continued). "Moreover, abnormal FD cells secrete the protein fibroblast growth factor 23 (FGF-23), which is responsible for hypophosphatemic rickets and, therefore, increased osteomalacia and fracture rates." (PMID 30484079, 2018). "Fibroblast growth factor 23 (FGF23) is considered a causative gene in tumor-induced osteomalacia (TIO), including low-phosphorus (P) rickets/osteomalacia with P reabsorption failure in the renal tubules and autosomal dominant hypophosphatemic rickets/osteomalacia (ADHR)." (PMID 29518087, 2018). "FGF23 expression in osteocytes is upregulated in several diseases, including osteomalacia." (PMID 28869564, 2017). "As a result, tumor-induced osteomalacia may affect the psoriasis clinical course by secreting a high amount of Fibroblast growth factor-23." (PMID 28852641, 2017). "The elevated level of FGF23 in right common iliac and external iliac veins detected by systemic venous sampling suggested that tumors localized in the right hallux responsible for the osteomalacia." (PMID 28193220, 2017). "Tumor-induced osteomalacia is often induced by various tumors, but it is often difficult to identify the localization of tumor, because most of the FGF23-producing tumors are small and could be observed in any part of the body." (PMID 27867811, 2016). "Ectopic FGF23 expression has only been reported in rare mesenchymal tumors associated with hypophosphatemic tumor-induced osteomalacia, due to renal phosphate loss - a feature not seen in myeloma." (PMID 25944690, 2015). "Mutation of the FGF23 protein which causes FGF23 to be resistant to cleavage by PHEX, occurring in autosomal dominant hereditary rickets, can result in increased circulating FGF 23 and a similar biochemical profile as oncogenic osteomalacia." (PMID 22934198, 2012). "Interestingly, this result differs from our previous report in which we describe that the osteomalacia and the high Opn levels in Fgf23−/−/PTH−/− mice persisted." (PMID 22615584, 2012). "FGF23 is a phosphaturic hormone that acts on the kidney to increase phosphate excretion; high-level FGF23 results in depletion of phosphate from the body, leading to osteomalacia." (PMID 22629419, 2012). "Interestingly, we noticed that in the long bone, the restoration of phosphate homeostasis by FGF-23 antibodies only partially rescued the bone-formation rate and osteomalacia, suggesting that DMP1 also plays a direct role in mineralization." (PMID 21542006, 2011). "Furthermore, osteomalacia may contribute to the pain sensation in FD, as inhibition of FGF23 using burosumab was accompanied by pain reduction in a child and an adult patient with severe FD/MAS." (PMID 40324210, 2025). "Excessive loss can occur due to elevated levels of fibroblast growth factor 23 (FGF-23), which impairs phosphate reabsorption in the kidneys and reduces phosphate absorption in the intestines, as observed in conditions such as X-linked hypophosphatemia and tumor-induced osteomalacia." (PMID 41146174, 2025). "Although tumoral calcinosis was caused by the impaired function of intact FGF23, mirroring the image of FGF23-related osteomalacia, we hypothesized that a case is also possible in which an autoantibody is developed that stimulates the secretion of intact FGF23." (PMID 34901334, 2021). "Additionally, whole genome sequencing for these cases revealed no mutations in the recognized genes related to hereditary FGF23-related hypophosphatemic rickets/osteomalacia or autoimmune diseases." (PMID 34901334, 2021). "Thus, oncogenic osteomalacia due to neoplastic FGF-23 secretion was suspected." (PMID 31963334, 2020). "FGF23 was shown to be positively associated with TmP/GFR in healthy subjects, and, in addition, phosphaturic activities of FGF23 have also been convincingly demonstrated in the genetically engineered animal models and in a patient with high FGF23 levels due to tumor-induced osteomalacia." (PMID 25200959, 2014).
osteomalacia (continued). "Recently, burosumab, a fully humanized monoclonal antibody against FGF23, was listed in the NHI drug price list in Japan for the indication of FGF23‐related hypophosphatemic rickets and osteomalacia." (PMID 38050660, 2024). "The identification of the role of FGF23 and PHEX improved the conventional therapy for XLH, since a human neutralizing antibody for FGF23, burosumab, was approved for the treatment of XLH and tumor induced osteomalacia." (PMID 34068220, 2021). "A recent study identified autoantibodies against PHEX, the gene responsible for XLH, in 5 of 13 patients with acquired FGF23-related osteomalacia without detectable PMTs, thereby defining a novel disease entity termed autoimmune osteomalacia (AIO)." (PMID 41691126, 2026). "Considering the high levels of FGF23 found in mice knocked-out for NF1 gene and in a NF1 woman with osteomalacia, the aim of this study was to investigate these results in NF1 pediatric patients to eventually provide biological insight into the possible pathogenesis of bone involvement in NF1." (PMID 40133996, 2025). "In the absence of Phex or Dmp1, an increase in systemic FGF23 levels in osteocytes results in enhanced phosphate excretion by the kidneys, leading to conditions such as rickets and osteomalacia." (PMID 41278197, 2025). "Indeed, Pi repletion further increased FGF23 and PTH levels, which exacerbated urinary Pi excretion, osteomalacia, and cortical bone expansion, similarly to studies performed in humans." (PMID 37943605, 2023). "Hypophosphatemic osteomalacia with raised plasma FGF23 level and no family history of rickets/osteomalacia was described in a female adult patient." (PMID 33660084, 2021). "In 2018, burosumab (Crysvita®; Kyowa Hakko Kirin Co., Ltd. and Ultragenyx Pharmaceutical Inc., Novato, CA, USA), a human neutralizing antibody for FGF23 was approved for the treatment of XLH in adults and children older than 1 year and in 2020 for the treatment of tumor induced osteomalacia." (PMID 34068220, 2021). "Moreover, while still possible given slightly elevated FGF23 levels, tumor-induced osteomalacia would likely not have improved without successful treatment of the inciting prostate cancer." (PMID 35145817, 2022). "Human FGF23 was simultaneously identified as a gene responsible for autosomal dominant hypophosphatemic rickets (ADHR) characterized by low serum phosphate levels, rickets, osteomalacia, lower extremity deformities, a short stature, bone pain, and dental abscesses." (PMID 26483756, 2015). "After searching the literature, we found neither a case of ovarian cancer-related osteomalacia nor detailed phosphate and FGF23 data of patients with ovarian cancer to draw a figure comparing serum phosphate and FGF23 levels purely in patients with ovarian cancer." (PMID 25181387, 2014). "Although serum fibroblast growth factor 23 (FGF23) was not measured, the clinical and biochemical profiles were highly consistent with tumor-induced osteomalacia (TIO)." (PMID 42221104, 2026). "Novel therapies that antagonize the systemic FGF23 excess in XLH children significantly improve rickets and osteomalacia, but do not have a dramatic effect on growth velocity in clinical trials and reports." (PMID 36371259, 2022). "Such a reduction in Opn levels could not be observed in Fgf23−/−/PTH−/− mice, and these mice showed sustained osteomalacia." (PMID 22615584, 2012).
rickets (148 papers, 2010 to 2026). Bone softening and weakening usually caused by deficiency or impaired metabolism of vitamin D. Deficiency of calcium, magnesium, or phosphorus may also cause rickets. "Burosumab is indicated and recommended for the treatment of X-linked hypophosphatemic rickets (XLH), another disorder of FGF23 excess in children with radiographic evidence of rickets from 1 yr of age and in symptomatic adults." (PMID 40297189, 2025). "Since rickets related to ENPP1 deficiency is also mediated by FGF23, the use of burosumab has been proposed as a therapeutic strategy in ARHR2 patients." (PMID 37871131, 2024). "A study revealed that individuals with vitamin D deficiency rickets exhibited reduced serum FGF23 levels, which subsequently rose following vitamin D therapy." (PMID 39346645, 2024). "Despite the metabolic connection between FGF23 and vitamin D, little is known about the status of FGF23 and Klotho in individuals with rickets induced by vitamin D deficiency." (PMID 37047636, 2023). "Genetic conditions leading to an increase in FGF23 concentration cause chronic low serum phosphate concentration and rickets." (PMID 37074534, 2023). "Elevated fibroblast growth factor 23 (FGF23) in X-linked hypophosphatemia (XLH) results in rickets and phosphate wasting, manifesting by severe bone and dental abnormalities." (PMID 38052774, 2023). "One of the important causes of rickets is chronic hypophosphatemia due to excessive actions of fibroblast growth factor 23 (FGF23), which is a bone-derived hormone that reduces serum phosphate level." (PMID 36531500, 2022). "The measurement of FGF23 levels is helpful in the diagnostic workup of phosphopenic rickets in order to differentiate between FGF23-mediated and other forms." (PMID 34910242, 2022). "Gambian children with a history of rickets-like bone deformities had a higher prevalence of anemia than community controls, and total-FGF23 concentration was negatively associated with hemoglobin concentration." (PMID 33675347, 2021). "This has been demonstrated already in children with X-linked hypophosphatemia, where treatment with anti-FGF23 antibody Burosumab improved linear growth and physical function, and reduced the pain and the severity of rickets." (PMID 32733380, 2020). "Blockade of FGF23 using Burosumab, has been demonstrated to be effective in control and improvement of rickets in patients with X-linked hypophosphataemia." (PMID 32982966, 2020). "Children carriers of any of these mutations have soft bones (rickets), growth retardation, poor dental development, and elevated serum FGF23 levels." (PMID 30820831, 2019). "After Tumor-Induced Osteomalacia was ruled out by extensive imaging, she was sent for genetic testing for hereditary rickets which showed a previously reported missense variant in FGF23." (PMID 30949368, 2019). "A recent open-label randomized trial showed that a FGF-23 blocking antibody (i.e. Burosumab) reduced the severity of rickets in patients with X-linked hypophosphataemia." (PMID 31791247, 2019). "In our case series of rickets patients, the biochemical profiles indicated urinary phosphate wasting associated with elevated plasma FGF23 and 1,25-dihydroxyvitamin D concentrations; vitamin D deficiency was discounted as causal factor." (PMID 25871880, 2015). "Deletion of Dmp1 in mice or mutations in DMP1 in humans causes hypophosphatemic rickets with an elevated circulating level of FGF23, which is responsible for the impaired renal tubular reabsorption of phosphate." (PMID 22879941, 2012). "It has been proposed that rickets in The Gambia is predominantly caused by a chronically low dietary calcium supply leading to increased FGF23, and associated urinary phosphate loss." (PMID 22465847, 2012). "Furthermore, FGF23 is the most critical biochemical marker for distinguishing nutritional vitamin D deficiency rickets from hypophosphatemic rickets, mainly in patients with an overlap of serum 25(OH)D concentrations." (PMID 38706696, 2024).
rickets (continued). "They suggested that low serum FGF23 might serve as a biochemical marker of vitamin-D-deficient rickets." (PMID 37047636, 2023). "In contrast, Fe deficiency was reported in autosomal dominant hypophosphatemic rickets, a rare form of rickets caused by mutations in the fibroblast growth factor 23 (FGF23) gene, implying that monitoring the Fe status is helpful for diagnosis, prognosis, and treatment of this genetic disease." (PMID 36726817, 2022). "However, the exact mechanism of PHEX gene mutation-mediated FGF23 upregulation, hypophosphatemia, and development of rickets is still unclear." (PMID 32733380, 2020). "The main hypothesis was that urinary phosphate wasting as a result of elevated FGF23 production caused by calcium deficiency is the underlying mechanism leading to rickets in children in Chakaria." (PMID 32276153, 2020). "Hypovitaminosis D is associated with greater plasma renin activity, inflammation, and higher blood pressure, and FGF-23 may play such roles in similar indirect ways, both of which are called phosphate-responsive hormones." (PMID 25033287, 2014). "In addition, cases of non-vitamin D deficiency rickets have been reported in Gambian children with chronically elevated circulating FGF23 concentrations." (PMID 22465847, 2012). "► High FGF23 and urinary phosphate loss in Gambian children with a history of rickets." (PMID 22023931, 2012). "Hypophosphatemic rickets include some disorders that may be associated with overproduction of fibroblast growth factor 23 (FGF23), namely FGF23-dependent forms, and disorders associated with a primary renal defect with normal concentrations of circulating FGF23, namely FGF23-independent forms." (PMID 38706696, 2024). "In addition, the discovery of the important role of FGF23 in the bone-kidney-parathyroid axis has led to a better understanding of the genetic conditions associated with phosphate disorders, the most common cause of phosphopenic rickets being XLH." (PMID 37047636, 2023). "Anti‐FGF23 neutralizing antibody therapy such as burosumab has emerged as a safe and effective treatment for X‐linked hypophosphatemia and can rapidly stabilize serum phosphate levels and lead to improvements in rickets, skeletal healing, and physical function." (PMID 31485552, 2019). "We published a case series of rickets from The Gambia, West Africa, in which the aetiology was unknown but was associated with a very low calcium intake and elevated plasma fibroblast growth factor 23 (FGF23)." (PMID 25871880, 2015). "It has been proposed that chronically low dietary calcium (Ca) supply resulting in a 1,25-dihydroxyvitamin D (1,25(OH)2D)-driven increase in FGF23 concentration and consequent excessive urinary (u) phosphate (P) loss may be contributing to the aetiology of this form of rickets." (PMID 23246670, 2013). "Following treatment with calcium and vitamin D, FGF23 concentrations (as measured with the Immutopics C-terminal FGF23 assay) remained consistently elevated over a 6–12 month period, suggestive of a long-standing, chronic abnormality of phosphate regulation predisposing to rickets." (PMID 22023931, 2012). "It has been proposed that a chronically low dietary calcium supply resulting in a 1,25-dihydroxyvitamin D (1,25(OH)2D)-driven increase in FGF23 concentration and consequent excessive urinary phosphate loss may be contributing to the aetiology of Gambian rickets." (PMID 22465847, 2012). "The FGF23 inhibitor burosumab improved growth, decreased rickets severity and improved symptoms and HRQL in paediatric phase 3 trials." (PMID 41634723, 2026). "Current evidence points to a fibroblast growth factor 23 (FGF23)-mediated mechanism, resulting in renal phosphate wasting, hypovitaminosis D, hypocalcemia, and secondary hyperparathyroidism." (PMID 41362568, 2025). "In a pediatric phase 3 trial, the FGF23 inhibitor burosumab improved rickets severity and bone biochemistry." (PMID 41030383, 2025).